SIRT1 (sirtuin 1)
Diseases named in the same sentence as SIRT1 in open-access papers (continued):
Sharing a sentence is not in itself a finding about the gene and the disease.
diabetes (continued). "Additionally, puerarin can upregulate HMOX1 and Sirt1-mediated autophagy, thereby mitigating diabetes-induced podocyte injury." (PMID 40337513, 2025). "Our results have potential clinical implications, as SIRT1 is recognized as a promoter of cell survival, angiogenesis and cell migration and the stress response in conditions where wound healing is impaired, such as diabetes." (PMID 40426868, 2025). "Moreover, the authors identified 11 diabetes-related genes with at least a ±2-fold difference in expression in the GDM/SIRT1(↑) group as compared with the NGT groups." (PMID 39861104, 2025). "MiR-34a inhibition and SIRT1 activation may be used as treatment options for diabetes mellitus-induced male infertility because the miR-34a/SIRT1 was found to regulate testicular apoptotic cell death." (PMID 40165339, 2025). "Interestingly, in type 2 diabetes mellitus, decreased SIRT1 was correlated with increased DNA damage, as also observed in our study through the elevated 8-OhdG amniotic fluid, confirming ongoing oxidative DNA damage." (PMID 40489580, 2025). "Genetic variations in the SIRT1 gene may contribute to the pathogenesis of type 2 diabetes mellitus (T2DM)." (PMID 40869934, 2025). "The present study aims to address this knowledge gap by investigating potential associations between the common SIRT1 promoter polymorphisms, rs12778366 and rs3758391, and T2DM and diabetes-related pregnancy complications in a well-defined cohort of Greek women." (PMID 40869934, 2025). "Moreover, the results suggest that hucMSC‐secreted EXOs enhance SIRT1/FoxO1/3a‐mediated mitochondrial function and ameliorate muscle atrophy in diabetes." (PMID 39871746, 2025). "Notably, SIRT1 downregulation in proximal tubules occurs early in diabetes, precedes albuminuria, and contributes to glomerular dysfunction via altered tubulo-glomerular crosstalk." (PMID 41470091, 2025). "Moreover, polyphenol-enriched cocoa treatment decreased PARP-1 activity and improved sirtuin-1 (SIRT-1) activity in animal models for hypertension and diabetes (SHR-STZ rats)." (PMID 39458649, 2024). "It is hoped that through further research, the SIRT1 gene can be used as a differential marker for depression in patients with diabetes, providing a more effective method for clinical diagnosis and treatment, thereby achieving early diagnosis and treatment of the disease." (PMID 39612426, 2024). "Hence, development of SIRT1 activators as potential treatments for diabetes warrants exploration in the future." (PMID 39372420, 2024). "Both podocyte‐specific Sirt1 overexpression and Sirt1 agonist treatment could attenuate diabetes‐induced podocyte apoptosis and effectively alleviate the progression of diabetic kidney disease in diabetic mice." (PMID 38506068, 2024). "Interestingly, Nimbidiol normalized Sirt1 expression in Akita mice, suggesting its potential renoprotective role in diabetes." (PMID 38835661, 2024). "Studies reporting decreased SIRT1 levels often involve cases with greater diabetes severity." (PMID 39944232, 2024). "In diabetes, SIRT1 suppresses low-grade micro-endothelial inflammation induced by chronic high glucose (HG) exposure by downregulating inflammatory cytokine production and nuclear factor κB (NF-κB) activity while promoting NO bioavailability and endothelial function." (PMID 39598406, 2024).
diabetes (continued). "miRNA‐195 overexpression observed in type 1 (T1DM) and type 2 (T2DM) diabetes mellitus hearts may lead to down‐regulation of sirtuin 1 (SIRT1), and impaired SIRT1 activity may affect oxidative metabolism, mitochondrial function and increase ROS production." (PMID 37845840, 2024). "SIRT-1 levels increased in patients with diabetes following an L-dAGEs diet." (PMID 39518960, 2024). "Clove is reported to improve insulin sensitivity, inhibit aldose reductase, prevent diabetic complications such as neuropathy and nephropathy, regulate SIRT1 to enhance glucose metabolism, and promote muscle glucose uptake, all of which assist the management of diabetes." (PMID 39519546, 2024). "Additionally, two proteins, silent information regulator 1 (Sirt1) and Voltage-dependent anion-selective channel protein 1 (VDAC1), implicated in regulating diabetes, were identified." (PMID 38510357, 2024). "Therefore, SIRT1 activity is closely related to regulation of glucose metabolism and lipid metabolism in metabolic diseases, such as diabetes and liver disease." (PMID 39372420, 2024). "Consistently, our results showed that NMN could restore the expression of Sirt1 in IVM oocytes of the mouse with diabetes." (PMID 38653987, 2024). "As such, SIRT1 promotes efficient energy utilisation and cellular defences in response to environmental challenges, whereas its dysregulation accelerates age-related diseases such as diabetes and cancer." (PMID 37530744, 2023). "AMPK/SIRT1 signaling pathway is known to play a critical role in diabetes development." (PMID 37723077, 2023). "The possible chronic metabolic stress in the patients, some also with diabetes, may have implied reduced expression of SIRT1." (PMID 37730614, 2023). "Our group also previously showed that mRNA SIRT1 expression in circulating leukocytes was significantly reduced in type 1 diabetes patients, which was accompanied by elevated serum SIRT1 levels in diabetes patients with coronary heart disease compared to patients without this condition." (PMID 36979007, 2023). "In addition to SIRT1, the damage of synapses in the brain structure of diabetic patients is also one of the reasons for diabetes‐related cognitive decline." (PMID 37248634, 2023). "Additionally, the hypoglycemic agent metformin was reported to mitigate tubulointerstitial fibrosis and oxidative stress in diabetes by enhancing autophagy through AMPK/Sirt1/FoxO1 pathway." (PMID 37020591, 2023). "The impact of SIRT1-interacting circRNAs in the regulation of SIRT1 has been assessed in diabetes and its complications, rheumatoid arthritis, chronic cerebral ischemia, osteoarthritis, intervertebral disc degeneration as well as malignant disorders, particularly glioma." (PMID 37441551, 2023). "Collectively, our findings suggested that YNJ could effectively ameliorate cardiomyopathy induced by diabetes possibly through SIRT1/Nrf2/NQO1 signaling." (PMID 37288289, 2023). "In the current study, our data suggested, for the first time, PHPB cloud improves diabetes-induced cognitive impairment in type 2 diabetic KK-Ay mice probably via inhibiting the generation of the AGEs and subsequently modulating SIRT1/insulin signaling pathway and reducing oxidative stress." (PMID 37259448, 2023). "The upregulation of cardiac FGF21 expression may increase SIRT1-mediated autophagy, which plays a key role in preventing diabetes-induced cardiac inflammation, oxidative stress, fibrosis, and dysfunction." (PMID 36843938, 2023). "Therefore, for the treatment of insulin resistance and diabetes, SIRT1 is a favorable pharmacological target." (PMID 37089941, 2023). "It is even more difficult to reach a conclusion because the effect of hyperglycemia on the expression of SIRT1 was tested in vivo while the modulatory effect of estradiol was tested in vitro, using cells isolated from animals with streptozotocin diabetes and normoglycemic controls." (PMID 37762053, 2023).
diabetes (continued). "So, Inhibition of SIRT1-FoxO1 pathway may be an important mechanism mediating diabetic induced cardiomyopathy." (PMID 36843938, 2023). "To investigate whether our findings hold true in patients with diabetes, we explored Sirt1 signaling and lipogenic transcriptional programs in myocardial specimens from diabetic patients and controls." (PMID 37957697, 2023). "In summary, activation of SIRT1 and Nrf2 signaling markedly enhances expression of antioxidant enzymes, attenuates oxidative damage, and is, thus, beneficial by retarding cardiac fibrosis induced by diabetes." (PMID 37288289, 2023). "About 25% of the patients suffered from diabetes, which might have influenced the SIRT1 and NAMPT results, pointing towards an unhealthy metabolic state in the patients, despite treated with anti-diabetic and lipid-lowering drugs." (PMID 37730614, 2023). "It should be noted that Sirt1 activation has been found to suppress the range of diabetic complications—nephropathy, retinopathy, neuropathy, cardiomyopathy, cataract—in rodent models of diabetes." (PMID 36135209, 2022). "In mice, SIRT1 prevented diabetes, particularly in aged mice." (PMID 35629426, 2022). "Therefore, increasing the expression of Sirt1 in tissues extracted from diabetic animals has been considered a method to treat diabetes and its complications." (PMID 35090502, 2022). "Taken together, these outcomes strongly indicate that both metformin and the CCB diet partly prevented diabetes-induced depletion of SIRT1 and Nrf2 and their down-stream antioxidant defences, whilst all these effects were prevented with the combination of CCB with metformin." (PMID 35204314, 2022). "SIRT1 is found to connect diabetes mellitus and non-alcoholic liver disease to HCM and DCM." (PMID 36385157, 2022). "We believe that SIRT1, which is suppressed by both diabetes and HIV infection, plays a key role in mediating the synergistic effects between diabetes and HIV and may explain why HIV infection aggravates DKD progression." (PMID 35795148, 2022). "An increasing body of research has discovered that hyperglycemia may affect AMPK activity and SIRT1 expression and that the severity of diabetes is negatively connected with AMPK/SIRT1 activity." (PMID 36262282, 2022). "We evaluated whether, in our model of early diabetes, changes occurred in specific miRNAs known to modulate the expression of genes related to calcium dynamics and SIRT1." (PMID 36355510, 2022). "Mitochondrial function is very important for insulin resistance in diabetes mellitus, and activation of SIRT1 and downstream target factors may be beneficial to the protection of mitochondrial function." (PMID 35739982, 2022). "SIRT1 is the most studied member of this enzymatic family, its dysregulation being involved in inflammation, redox stress, neurodegeneration, fat accumulation, diabetes, tumorigenesis, etc.." (PMID 35807694, 2022). "Additional research performed on a mouse model of induced diabetes has pointed out the function of endothelial microRNA-34a which can be upregulated by oxidative stress, thus leading towards endothelial dysfunction mediated by sirtuin-1 inhibition." (PMID 36359402, 2022). "cPWWP2A directly regulates pericytes biology but indirectly regulates ECs biology via EVs carrying cPWWP2A, which inhibited miR-579 activity, increased expression of angiopoietin 1/occludin/SIRT1, and ultimately alleviates diabetes-induced retinal vascular dysfunction." (PMID 36686474, 2022). "EX-4 was shown to modulate SIRT1 in rat retinal cells at early diabetes stages." (PMID 35409409, 2022). "In this study, we might shed light on the molecular mechanism of hyperglycemia/diabetes‐induced AD mediated by SIRT1 between brain vasculature and neuronal cells." (PMID 36073820, 2022). "Further analysis showed that acacetin suppressed atherosclerosis aggravated by diabetes may be mediated by activating the Sirt1/Sirt3/AMPK signaling pathway to protect mitochondrial function." (PMID 35677446, 2022).
diabetes (continued). "However, because data on SIRT1 are scarce, little is known about its role in metabolism or its effect on diabetes." (PMID 36430361, 2022). "Moreover, PGC1-α activation has been shown to be involved in mitochondrial remodeling via the AMPK/Sirt1 axis in response to diabetes medication therapy." (PMID 35659361, 2022). "Moreover, Quercetin was found to reduce oxLDL-induced oxidative damage by upregulating AMPK and SIRT1 activity; and reduce oxidative damage in the liver and kidney tissues, and NF-kB levels by increasing SIRT1 in diabetes model." (PMID 35935939, 2022). "It has been shown, that palmitate treated insulinoma cell line clone 1E (INS-1E) displayed decreased SIRT1 levels, however, RES enhanced it expression as well as the genes associated with mitochondrial biogenesis and lipid metabolism providing the evidence that SIRT1 activation mitigates diabetes." (PMID 34034759, 2021). "The results of present study indicate that calystegines act via SIRT1 in PA-induced HepG2 cells providing an insight into the mechanism by which these substances may prevent diabetes and supporting their application as a clinical intervention." (PMID 34034759, 2021). "Therefore, the primary aim of this study was to evaluate the serum levels of Klotho and SIRT1 in patients with high blood pressure and diabetes and the patients who have both diseases simultaneously." (PMID 34670596, 2021). "Exenatide is known to improve diabetes through SIRT1 restoration." (PMID 34434166, 2021). "Resveratrol also prevents oxidative stress induced by diabetes in EPCs via sirtuin-1 activation." (PMID 34576323, 2021). "Hence, this study aimed to investigate the role of FKBPL and SIRT-1 in pre-gestational (type 1 diabetes mellitus, T1D) and gestational diabetes mellitus (GDM)." (PMID 34149611, 2021). "SIRT1 is considered as a potential target for the treatment of diabetes and its complications." (PMID 33748285, 2021). "SIRT1 can negatively regulate vascular calcification in diabetes." (PMID 34071497, 2021). "There is no extra benefit for combining Sirt1 and Sirt3 activators for the treatment of diabetes and associated cardiac complication." (PMID 33668369, 2021). "It has been shown that SIRT1 activation has beneficiary effects on aging and metabolic disorders such as metabolic syndrome and diabetes mellitus, and on chronic inflammatory diseases such as arthritis and atherosclerosis, and also on DNA damage and oxidative stress." (PMID 34670596, 2021). "The severity of diabetes in our study was not high as we did not include the patients who received treatment for diabetes in the study and HbA1C was about 7.5%, while in studies in which the level of Klotho and SIRT1 reduced, the severity of diabetes was higher." (PMID 34670596, 2021). "Serum levels of SIRT1 and Klotho in pre-diabetes were lower than in healthy controls and diabetics." (PMID 34670596, 2021). "More recently, natural antioxidants including epigallocatechin and naringenin have been shown to reduce oxidative damage in ECs via SIRT1, and an intermittent fasting regimen was found to ameliorate vascular dysfunction in a murine model of diabetes by activating the SIRT1 pathway." (PMID 35002720, 2021). "This altered expression of Sirt1 was reversed ex vivo with a DNA-methylation inhibitor and in vivo with the antioxidant N-acetyl-cysteine, suggesting that Sirt1 expression in the heart of offspring from dams with diabetes is epigenetically regulated and affected by an oxidative environment." (PMID 34803741, 2021). "Limited studies have examined the expression of SIRT1 and Klotho in pre-diabetes." (PMID 34670596, 2021). "It is noteworthy that the reduction in carnitine palmitoyltransferase (CPT) level observed in diabetes is a rate-limiting step underlying the delivery of long-chain fatty acids to mitochondria, while PGC-1α and SIRT1 may regulate its expression." (PMID 33171690, 2020).
diabetes (continued). "SIRT1 is involved in various physiological processes including aging, energy metabolism, and stress responses and therefore has been considered a potential therapeutic target for multiple diseases like cancer, Alzheimer’s, diabetes, and atherosclerosis." (PMID 32106265, 2020). "The positive effect of MNAM on insulin sensitivity in diabetes was abrogated, suggesting that the SIRT1/FOXO1 signal pathway could regulate the effects of MNAM in obese T2DM model." (PMID 32280711, 2020). "In generally, SIRT1 is decreased in conditions of chronic metabolic stress, oxidative stress, or hypoxia that drive the pathophysiology of age-related diseases including diabetes, cardiovascular, NAFLD and renal diseases." (PMID 32365537, 2020). "The study suggests that medications that prevent NAD+ depletion induced by diabetes mellitus and molecules that activate SIRT1 may provide a therapeutic intervention for diabetic neurodegeneration in the central nervous system." (PMID 32466541, 2020). "The SIRT1 signaling pathway may be a key mechanism for alleviating diabetes-related neurodegenerative diseases." (PMID 32312941, 2020). "Moreover, treatment with the SIRT1 activator resveratrol attenuates the diabetes-induced downregulation of SIRT1, accompanied by reduced expression of HMGB1 and RAGEs." (PMID 32722545, 2020). "Diabetes-triggered mir-23b-3p was shown to induce OxS via decreasing expression of SIRT1 and Nrf2." (PMID 32962281, 2020). "Resveratrol may confer protection against the diabetes-induced breakdown of BRB through SIRT1 upregulation and HMGB1 downregulation." (PMID 32722545, 2020). "Thus, SIRT1 activation is currently under investigation as a therapeutic approach for various diseases, including diabetes and its vascular complications." (PMID 33150239, 2020). "Panax notoginseng (Burkill) F.H.Chen and panax notoginseng saponins could protect kidney from diabetes via the mechanism of upregulating SIRT1, therefore activating antioxidant proteins and inhibiting inflammation by decreasing the inflammatory cytokines." (PMID 33854427, 2020). "Confirming this speculation, our group has demonstrated the beneficial effect of SIRT1 activation in diabetes‐induced endothelial dysfunction." (PMID 32628815, 2020). "Indeed MMP9 can be the link: while in diabetes MMP9 is overexpressed due to SIRT1-deficit, there are also results confirming activation of MMP9 in the diabetic retina by extracellular signal-regulated kinase (ERK) MAP kinase pathway." (PMID 32204537, 2020). "Moreover, the multiple benefits for targeting SIRT1 to prevent various angiocardiopathy that involved the status of diabetes were further revealed by numerous finds." (PMID 31210844, 2019). "Therefore, SIRT1 and 3 activators have been proposed to prevent and counteract metabolic age-related diseases, such as type 2 diabetes mellitus (T2DM)." (PMID 31557786, 2019). "These factors may affect cellular pathways involved in metabolic diseases such as diabetes, indicating that Sirt1 is related to the process of diabetes or diabetes-related diseases." (PMID 31583043, 2019). "However, we are still not certain about the mechanisms of aerobic exercise leading to the activation of the AMPK/Sirt1 signaling pathway in the hippocampus under diabetes." (PMID 30911292, 2019). "This study suggests that resveratrol may have a neuroprotective action through activation of Sirt1 signaling in diabetes and AD with concurrent onset." (PMID 32038127, 2019). "Collectively, those data suggest that THC could attenuate diabetes-induced oxidative stress by activating the SIRT1-involved antioxidative pathway in DCM." (PMID 31210844, 2019). "Taking into account the metabolic impacts of SIRT1 and fetuin-A, management of their levels could be effective in diabetes control." (PMID 29803203, 2019).